CDK4 (cyclin dependent kinase 4)
Diseases named in the same sentence as CDK4 in open-access papers (continued):
Sharing a sentence is not in itself a finding about the gene and the disease.
breast cancer (continued). "In terms of second-line efficacy, the MONALEESA-3 and PALOMA-3 studies both evaluated the combination of CDK4/6 inhibitors with fulvestrant in HR+/HER2− advanced breast cancer patients but differed in terms of patient populations and outcomes." (PMID 40136365, 2025). "Of note, CDK4/6 inhibition has been approved by the FDA for ER+ breast cancer; however, its effectiveness in TNBC was less clear in light of their negative RB status." (PMID 40764669, 2025). "CDK4/6 inhibitors significantly suppress disease progression in HR+/HER2- breast cancer, demonstrating marked therapeutic synergy when combined with endocrine therapies." (PMID 40421216, 2025). "Overactivation of FGFR signaling was also observed in CDK4/6is-resistant breast cancer, with FGFR1/2 overexpression or amplification correlating with reduced sensitivity." (PMID 40244377, 2025). "Cyclin-dependent kinases 4 and 6 (CDK4/6) are central regulators of cell cycle progression and frequently dysregulated in cancers, including breast cancer." (PMID 40038413, 2025). "This meta-analysis incorporated data from four pivotal clinical trials (Natalee, monarchE, PENELOPE-B, and PALLAS) that assessed the efficacy of CDK4/6 inhibitors in the adjuvant treatment of HR+/HER2− early breast cancer." (PMID 41228331, 2025). "Our study supports the rationale of continued CDK4/6 inhibition beyond progression as a viable option for carefully selected patients of ER+ advanced breast cancer." (PMID 40427107, 2025). "The therapeutic landscape of HRpos/HER2neg advanced breast cancer (aBC) has changed, particularly with the introduction of cyclin-dependent kinase 4/6 (CDK4/6) inhibitors." (PMID 41534416, 2025). "Despite these limitations, our study provides valuable insights into the efficacy of denosumab and zoledronic acid in preventing SREs in patients with stage 4 breast cancer receiving CDK4/6 inhibitors." (PMID 40005476, 2025). "Among 464 patients diagnosed with breast cancer, 10 (2.1%) were found to have confirmed interstitial lung disease (ILD) associated with CDK4/6 inhibitors." (PMID 40142360, 2025). "Dysregulation of the CDK4/6 pathway leads to increased cell proliferation, making inhibition of these kinases a promising approach to cancer treatment, with some CDK4/6 inhibitors currently approved for the treatment of breast cancer." (PMID 41471075, 2025). "In Calgary, Alberta, the Arthur J.E. Child Comprehensive Cancer Center includes a GPO-led clinic that manages patients with breast cancer who are eligible for adjuvant ET plus CDK4/6 inhibitor therapy or adjuvant olaparib." (PMID 40710212, 2025). "When CDK4/6 is inhibited in breast cancer cells with low CCNE1, early adaptation occurs (up to 72 h), resulting in CDK2 activation and increased cyclin E2 (CCNE2) expression, eventually leading to S phase entry." (PMID 40075623, 2025). "The IFN pathway was associated with the immunosuppressive microenvironment in ER+ breast cancer and resistance to CDK4/6i." (PMID 39667501, 2025). "This study aims to explore the impact of follow-up duration on the efficacy of CDK4/6 inhibitors in HR+, HER2-breast cancer patients in the early setting, especially in high-risk N0 or Stage II patients." (PMID 40717978, 2025). "A study focusing on the luminal A breast cancer subtype found that CDK4/6is reduces expression of the cystine transporter SLC7A11 by inhibiting SP1 binding to the SLC7A11 promoter region." (PMID 40244377, 2025). "Although the efficacy of CDK4/6 inhibition HR+/HER2− breast cancer cells was well‐established, effects of targeting CDK4/6 in CRC remain largely unexplored." (PMID 39968498, 2025). "In this study we identified genes whose loss-of-function leads to insensitivity to combination endocrine and CDK4/6 inhibitor therapy in ER+ breast cancer models using human genome-wide CRISPR/Cas9 screens." (PMID 40826108, 2025).
breast cancer (continued). "The importance of lysosomes in CDK4/6 inhibitors resistance was also reported in breast cancer, where destabilizing lysosomes with chloroquine, seremesine, or azithromycin had a sensitizing effect in resistant triple-negative breast cancer cells." (PMID 40699853, 2025). "Cyclin-dependent kinase 4 and 6 inhibitors have become a novel form of adjuvant therapy for the treatment of advanced or metastatic breast cancer characterised by positive hormone receptors and human epidermal growth factor receptor 2 (HER-2) negative." (PMID 40075608, 2025). "There are two ongoing phase III studies of CDK4/6 inhibitors applied to the adjuvant treatment of HR+/HER2- early breast cancer, dalpiciclib (SHR6390-III-303, NCT04842617) and TQB3616 (TQB3616-III-03, NCT05780567)." (PMID 40002156, 2025). "Research on key cell cycle regulatory proteins, such as CDK4/6 inhibitors, has provided new insights into the development of novel therapeutic strategies for breast cancer." (PMID 40708936, 2025). "Both trials confirmed the benefit of CDK4/6 inhibitors combined with fulvestrant in advanced breast cancer." (PMID 40136365, 2025). "This study offers a comprehensive overview of adverse events related to CDK4/6 inhibitors in the treatment of HR + /HER2- advanced breast cancer." (PMID 41259313, 2025). "A partitioned survival model was developed to compare costs and effectiveness of first-line (CDK4/6i-first) versus second-line (CDK4/6i-second) CDK4/6 inhibitor strategies among Chinese women with advanced HR+/HER2- breast cancer." (PMID 41383485, 2025). "The aim of this study is to evaluate the impact of demographic, clinical, and tumor-related characteristics on the efficacy of CDK4/6 inhibitors in a cohort of patients with metastatic HR+/HER2− breast cancer." (PMID 40244189, 2025). "Although rare, loss-of-function mutations in the cadherin superfamily member FAT1 have also been associated with CDK4/6is resistance, potentially due to CDK6 overexpression in ER+ breast cancer patients." (PMID 40244377, 2025). "In recent years, targeted therapy with CDK4/6 inhibitors combined with endocrine therapy has made significant progress in the treatment of early and advanced HR + breast cancer, making it an important treatment option for HR + breast cancer." (PMID 41282629, 2025). "While standard treatments mirror those for female breast cancer, emerging options such as cyclin-dependent kinase 4 and 6 (CDK4/6), and poly(ADP-ribose) polymerase (PARP) inhibitors, immunotherapy, and precision medicine are reshaping management." (PMID 41502531, 2025). "The development of CDK4/6 inhibitors has revolutionized breast cancer (BC) treatment; however, their potential ocular toxicity is often underestimated." (PMID 41282629, 2025). "Perturbation of the retinoblastoma (Rb) pathway, a key modulator of cell cycle advancement, has prompted the evolution of CDK4/6 inhibitors as a treatment strategy for breast carcinoma." (PMID 40456804, 2025). "For example, CDK4/6 inhibition stimulates type III interferons production in breast carcinoma and other solid tumors." (PMID 40175357, 2025). "In the therapeutic setting, CDK4/6 inhibitors as oral maintenance therapy in early breast cancer and immune checkpoint inhibitors (Pembrolizumab) for triple-negative breast cancer (BC) are noteworthy." (PMID 40261372, 2025). "Cyclin-dependent kinase 4 and 6 (CDK4/6) inhibitors have significantly improved the treatment of HR+/HER2− breast cancer." (PMID 40149372, 2025). "Breast cancers are relatively rare in men, accounting for less than 1% of all BC; however, treatment with CDK4/6 should be tested." (PMID 40149372, 2025). "We summarized all efficacy outcomes of CDK4/6 inhibitors for breast cancer and reported them in narrative form." (PMID 38240835, 2024). "In luminal breast cancer, hypophosphorylation and hence activation of Rb by CDK4/6i induces a tumor cell phenotype resembling cellular senescence." (PMID 38047585, 2024).
breast cancer (continued). "We have also reported synergistic inhibitory efficacy achieved with our NB compounds and proteasome inhibitors in breast cancer and multiple myelomas and with CDK4/6 inhibitors in ER-positive breast cancer." (PMID 38980505, 2024). "In patients with advanced and metastatic ER+ breast cancer, the addition of CDK4/6 inhibitors to endocrine therapy has significantly increased survival rates." (PMID 38791941, 2024). "Although combined CDK4/6i and endocrine therapy has significantly improved outcome of patients with advanced ER+ breast cancer, progression is expected and thus new therapeutic strategies to overcome treatment resistance are urgently needed." (PMID 39931212, 2024). "evaluates CDK4/6 inhibitors’ toxicity in metastatic breast cancer, stressing personalized treatment strategies due to varying drug profiles." (PMID 38699635, 2024). "As a result, the US Food and Drug Administration (FDA) authorized the use of all three CDK4/6i drugs in the management of patients who have advanced or metastatic HR+/HER2− breast cancer." (PMID 38983782, 2024). "For general HR-positive, HER2-negative breast cancer, endocrine therapy with CDK4/6 inhibitor is a standard therapy." (PMID 39969377, 2024). "In hormone receptor-positive and HER2-negative breast cancers, a growing number of revolutionary personalized therapies are in clinical use or trials, such as CDK4/6 inhibitors, immune checkpoint inhibitors, and PIK3CA inhibitors." (PMID 39796647, 2024). "ALND not only removed the potential metastatic lymph nodes but also provided more detailed lymph node staging for clinical adjuvant therapy, especially for CDK4/6 inhibitors usage in luminal breast cancer." (PMID 39544961, 2024). "Cdk4/6 inhibitors in combination with endocrine therapy are used to treat advanced ER+/HER2− breast cancers." (PMID 39441926, 2024). "Further research should explore the specific mechanisms underlying QT prolongation and evaluate its clinical implications for the safe and effective use of CDK4/6 inhibitors in breast cancer treatment." (PMID 39254653, 2024). "Currently, endocrine therapy (ET) combined with a cyclin-dependent kinase 4/6 inhibitor (CDK4/6i) is the standard of care in the first-line setting for patients with HR + /HER2 − advanced breast cancer (ABC)." (PMID 39177931, 2024). "In this study, we employed a network meta-analysis to evaluate the efficacy (ORR, DCR, OS, and PFS) and safety (total AREs, neutropenia, diarrhea, and fatigue) of CDK4/6 inhibitors combined with ET in HR+/HER2-breast cancer." (PMID 38832268, 2024). "Since receiving approval from the Food and Drug Administration (FDA) in 2015, CDK4/6i treatment has become widespread worldwide and the standard of care for HR-positive advanced breast cancers." (PMID 39133334, 2024). "Treatment with CDK4/6 inhibitors can induce senescence in specific cancer cells, including oestrogen receptor (ER)‐positive breast cancer, lung cancer, melanomas and liposarcoma." (PMID 39270064, 2024). "Previous studies have shown that CDK4 is upregulated in a variety of tumors and that inhibition of CDK4 expression improves clinical management of melanoma, breast cancer, GB, and liposarcoma." (PMID 39155374, 2024). "The addition of a CDK4/6 inhibitor is an obvious and promising treatment for older patients with early breast cancer, but the results of the Appalachies study are still pending." (PMID 39405593, 2024). "Here, we demonstrate that MYC amplification confers resistance to CDK4/6i in bladder, prostate and breast cancer cells." (PMID 38424044, 2024). "This study applied meticulous experimentation involving HR+/HER2-low cell lines and animal models, highlighting the role of the HER2 pathway in the efficacy of CDK4/6 inhibitor combined with endocrine therapy for HR+/HER2-low breast cancer." (PMID 39730704, 2024). "Subsequent to flavopiridol, three selective CDK4/6 inhibitors—palbociclib, ribociclib, and abemaciclib—have secured regulatory approvals in breast cancer." (PMID 37955764, 2024).
breast cancer (continued). "To identify gene expression alterations associated with resistance to combined endocrine therapy and CDK4/6i, we performed RNA sequencing of two ER+ breast cancer cell models resistant to this combined therapy." (PMID 39931212, 2024). "This study aims to investigate two different CDK4/6i (palbociclib and ribociclib) in patients with HR-positive mBC and relapsed breast cancer (rBC) and provide real-world evidence of safety and treatment strategies in the Asian population." (PMID 39133334, 2024). "The indication of these inhibitors for ER + /HER2- breast cancer can be attributed to the specific dependency of these tumors on cyclin D1 and CDK4/6." (PMID 38831405, 2024). "In the systemic treatment of metastatic or advanced HR+/HER2– breast cancer, CDK4/6 inhibitors such as palbociclib, abemaciclib, or ribociclib are commonly used." (PMID 38327984, 2024). "Despite the crucial clinical benefits of CDK4/6 inhibitors in HR+ breast cancer, studies have shown that approximately 20% of patients with HR+ breast cancer develop primary resistance to CDK4/6 inhibitors, and more than 30% experience secondary resistance." (PMID 39196911, 2024). "Various endocrine therapy strategies, including SERD, SERM, AI, GnRHa, and inhibitors of PI3K, AKT, mTOR, and CDK4/6, are being explored to enhance the immune response in breast cancer." (PMID 39188717, 2024). "Cyclin-dependent kinase 4/6 inhibitors (CDK4/6i) have significantly improved the survival of patients with hormone receptor-positive HER2-negative advanced breast cancer (ABC)." (PMID 39120877, 2024). "Overexpression of CDK4 has been observed in a variety of cancers including breast cancers, glioblastomas multiforme, gliomas, and meningiomas." (PMID 39795915, 2024). "Cyclin-dependent kinase 4 and 6 inhibitors (CDK4/6i) are the standard agents for treating patients with estrogen receptor-positive and human epidermal growth factor receptor 2-negative advanced breast cancer (ER + HER2 − ABC)." (PMID 38684839, 2024). "In hormone receptor-positive (HR+), human epidermal growth factor receptor 2-negative (HER2-) breast cancer, the dysregulation of the CDK4/6 pathway leads to uncontrolled cellular proliferation, which is central to disease progression." (PMID 39766060, 2024). "For advanced breast cancer patients receiving aromatase inhibitor (AI) and CDK4/6 inhibitor therapy, monitoring the emergence of estrogen receptor 1 (ESR1) mutations holds potential clinical utility." (PMID 39184861, 2024). "Specifically, it focuses on using CDK4/6 inhibitors with hormone therapy for treating metastatic HR+/HER2- breast cancer in patients aged 70 and older." (PMID 39456537, 2024). "Over the last decade, an increasing amount of evidence supporting a clear clinical benefit of CDK4/6is has led to a rising rate of prescription of these drugs for ER + /HER2- breast cancer." (PMID 38831405, 2024). "The use of Cyclin-Dependent kinase 4 and 6 (CDK4/6) inhibitors has profoundly changed the challenge of endocrine therapy (ET) resistance in hormone receptor-positive (HR+)/HER2-negative (HER2−) breast cancer." (PMID 38240835, 2024). "Meanwhile, studies have shown that adding CDK4/6 inhibitors to ET improves survival not only in advanced breast cancer but also in early breast cancer." (PMID 39405593, 2024). "The monarchE study added the CDK4/6 inhibitor abemaciclib to the care of women with oestrogen-positive (ER+) breast cancers." (PMID 39272930, 2024). "The Chinese breast cancer guidelines recommend a combination of CDK4/6 inhibitors and aromatase inhibitors (AI) as the preferred treatment for HR + advanced breast cancer without endocrine therapy, including abemaciclib, palbociclib, ribociclib." (PMID 39161906, 2024). "Together, our data suggest that RET is a driver of cell cycle progression at the G2-M phase of the cell cycle in combined CDK4/6i- and fulvestrant-resistant ER+ breast cancer cells." (PMID 39931212, 2024).
breast cancer (continued). "The ER+/luminal A subtype is the most common subtype of breast cancer and its current treatment strategies include endocrine therapy and targeted therapy along with chemotherapy and radiotherapy, or with CDK4/6 inhibitors at an advanced stage." (PMID 39195531, 2024). "We also tested combination therapy with fulvestrant and palbociclib, an inhibitor of CDK4/6 used with anti-estrogen therapy for patients with metastatic ER+ breast cancer." (PMID 39480488, 2024). "In this study, we aimed to evaluate the efficacy and accuracy of locoregional RT in advanced breast cancer patients treated with CDK4/6 inhibitors in a first-line setting." (PMID 39065777, 2024). "Although CDK4/6 inhibitors have had great value in the treatment of metastatic HR+/HER2− breast cancer, a better understanding of their value is needed in early stage HR+/HER2− breast cancer for the following reasons." (PMID 38448600, 2024). "Palbociclib49, an FDA-approved CDK4/6 inhibitor for breast cancer, blocked S1900 phosphorylation of CAD in KSHV de novo infected HOKs and KSHV-positive BCBL-1 lymphoma cells." (PMID 38365882, 2024). "CDK4/6i therapy of treatment-naïve luminal breast cancers induces an Rb-dependent phenotype resembling cellular senescence." (PMID 38047585, 2024). "Targeting CDK4/6 in breast cancer has been demonstrated to be initially effective but often, resistance develops." (PMID 38961064, 2024). "Fulvestrant was the first-in-class approved SERD and is used to treat ER+ metastatic and advanced breast cancer alone, as well as in combination with CDK4/6 inhibitors." (PMID 38791941, 2024). "One CDK4/6 inhibitor that has been approved by the FDA for the management of HR+ breast cancer is abemaciclib." (PMID 38983782, 2024). "Significant advancements have been made in the development of cancer therapies targeting cell cycle proteins, such as CDK4/6, resulting in highly effective and precise treatments for breast cancer." (PMID 38570712, 2024). "Abemaciclib is an oral, continuously administered CDK4/6 inhibitor used for treating patients with advanced breast cancer who are HR-positive and HER2-negative." (PMID 39606228, 2024). "Approximately 20% of patients with HR+ breast cancer developed primary resistance to CDK4/6 inhibitors, and more than 30% experienced secondary resistance." (PMID 39196911, 2024). "CDK6 is a clinically important target, since CDK4/6 inhibitors are used in treatment of ER+ breast cancer, and clinical trials are currently evaluating their effectiveness in TNBC." (PMID 39171293, 2024). "With the gradual disclosure of RCTs for CDK4/6 inhibitors in combination with ET in patients with HR+/HER2− breast cancer, an increasing number of MAs and SRs are summarizing and analyzing clinical efficacy from multiple perspectives." (PMID 38240835, 2024). "Newer treatments attempting to improve outcomes for women with ER+ breast cancer have targeted the cyclin-dependent kinase 4 and 6 (CDK4/6) protein pathways within breast cancer cells." (PMID 39272930, 2024). "These CDK4/6i have substantially enhanced treatment options for patients with HR+ breast cancer by targeting the cell cycle regulation process, which plays a pivotal role in cancer growth." (PMID 38464732, 2024). "In patients with advanced HR+, HER2-negative breast cancer, the combination of endocrine therapy with a CDK4/6 inhibitor is considered the standard of care in first-line therapy, given the ability of this treatment to prolong patients’ PFS." (PMID 38791880, 2024). "In summary, CDK4/6i combinations stand as the primary choice for first-line endocrine therapy in endocrine-sensitive HR + /HER2- advanced breast cancer." (PMID 38409585, 2024). "INX-315 is currently being clinically investigated to determine its safety and efficacy in both CCNE1-amplified cancers as well as in CDK4/6i-resistant breast cancer (NCT05735080)." (PMID 38047585, 2024).